TNF (tumor necrosis factor)
Diseases named in the same sentence as TNF in open-access papers (continued):
Sharing a sentence is not in itself a finding about the gene and the disease.
tumor (continued). "Compared with paired surgical margins, tumour tissues exhibited an inflammatory shift characterised by increased IL-1β and IL-6 alongside reduced TNF-α, IFN-γ, IL-12 and IL-2." (PMID 41465261, 2025). "Inflammatory cytokines (e.g., IL-6, TNF-α) in the tumor microenvironment stimulate PCT production, rapidly elevating its blood concentration." (PMID 40400626, 2025). "Conversely, MCs can also exhibit anti-tumor properties by releasing TNF-α, granzyme B, and IL-17, which enhance anti-tumor immunity." (PMID 40272538, 2025). "TNF exerts tumor-suppressive effects in vivo and induces cytotoxicity in PMNs and T effector cells, which kill tumor cells, virus-infected cells, and other cells and inhibit viral replication." (PMID 40177420, 2025). "IHC analysis of TNF‐α and IL‐6 in tumour tissues showed that GlyGCC (+) EVs increased TNF‐α and IL‐6 expression compared to control EV treatment." (PMID 40326665, 2025). "TNFSF14, also known as LIGHT, is a member of the tumor necrosis factor (TNF) superfamily that plays a pivotal role in modulating anti-tumor immune responses." (PMID 40496862, 2025). "First, an increase in forward scatter CV after Pam3CSK4 stimulation suggests WBC hyperactivity, which can lead to the release of cytokines and chemokines like TNF, IL-6, and IL-8, promoting tumor cell proliferation, invasion, and metastasis." (PMID 39960903, 2025). "NK cells produce cytokines such as IFN-γ and TNF-α, which enhance the anti-tumor activity of other immune cells, including dendritic cells (DCs) and T cells." (PMID 39911388, 2025). "Consistent with the pseudotime analysis, peripheral T, fibroblastic and epithelial tumour‐prone cells at KO state exhibited activation of inflammation‐related pathways, including the TNFα, NF‐κB, hypoxia, and JAK‐STAT signalling pathway." (PMID 40887856, 2025). "IL-6 and TNF-α promote tumor progression by enhancing inflammation and creating an immunosuppressive microenvironment, while MCP-1 recruits monocytes and macrophages, potentially aiding immune evasion and metastasis." (PMID 40171218, 2025). "The chemotaxis of mast cells into the GC microenvironment is facilitated by CXCL12-CXCR4 signaling, while tumor-derived TNF-α activates the NF-κB pathway to up-regulate PD-L1 expression." (PMID 40091086, 2025). "They exert anti-tumor effects through the secretion of pro-inflammatory cytokines like TNF and IL-2, generation of reactive oxygen and nitrogen species, and enhanced antigen presentation to T cells." (PMID 41417432, 2025). "The development into M1 macrophages leads to increased production of pro-inflammatory cytokines (IL1-β, TNF-α, and IL-6), and support of the adaptive anti-tumor activity." (PMID 41440002, 2025). "The capacity of CD4 T cells to reinforce tumor cytostasis parallels findings that Th1 CD4 T cells can induce senescence-like states in cancer cells through TNF-α and IFN-γ secretion." (PMID 40299790, 2025). "Adhesion molecules on peritoneal mesothelial cells can interact with receptors, such as CD44, on tumor cells, resulting in cytokine and Tumor Necrosis Factor alpha (TNFa) release, facilitating tumor cell attachment and invasion into the peritoneum." (PMID 41082053, 2025). "To evaluate the effects of oral probiotics CB and AKK on the immune response in 4 T1 tumor‐bearing mice, we measured the changes in levels of tumor necrosis factor (TNF‐α), IL‐6, and IL‐10 in both the tumors and serum of the mice." (PMID 40497373, 2025). "In contrast, in the hypothalamus, the expressions of TNF-α, IL-6, IL-1β and NF-κB were elevated in the Tumor group of mice, which were all reversed by the treatment of PVSO group (p < 0.05)." (PMID 40993108, 2025). "Our results showed that reuterin pretreatment significantly enhanced macrophage‐mediated tumor cell killing, accompanied by increased NO and TNF‐α production upon stimulation with TCM." (PMID 40587842, 2025).
tumor (continued). "T and B lymphocytes, fibroblasts, tumor cells, keratinocytes, neutrophils, endothelial cells, neurons, mast cells, and NK cells are also TNF-α producers." (PMID 39570546, 2025). "In the TME, type 1 macrophages (M1) initially invade the tumor in an attempt to destroy tumor cells by secreting cytokines such as IL‐1 and TNF‐α, which activate CD8 + T lymphocytes and natural killer (NK) cells." (PMID 40553053, 2025). "For example, FUOM was strongly implicated in Th17 cell differentiation, a pathway known to drive tumor‐promoting inflammation, while H2BC21 was associated with TNF and IL‐17 signaling, which are integral to immune evasion and chronic inflammation in cancer." (PMID 40817807, 2025). "Curcumin is able to decrease levels of pro-inflammatory cytokines such as interleukin-6 (IL-6) and tumor necrosis factor-alpha (TNF-α) in order to control the tumor immune microenvironment." (PMID 40728996, 2025). "In parallel, IL-10 reduces the production of pro-inflammatory cytokines such as IL-1β and TNF-α in neutrophils, further stabilizing the N2 phenotype and dampening anti-tumor immune responses." (PMID 40281554, 2025). "T cells regulated tumour cells selectively through the TNF signalling pathway, while exerting minimal effects on non‐malignant epithelial cells." (PMID 40770837, 2025). "The results showed that Z526 diminished NF-κB transcriptional activity, which was enhanced by TNF-α or CMs of cachectic tumor cells." (PMID 39759112, 2025). "TNF-α plays a complex, context-dependent role in tumor biology, functioning as both a tumor suppressor and promoter." (PMID 41302997, 2025). "Glucose and fructose can induce the expression of pro-inflammatory cytokines such as interleukin-6 (IL-6) and tumor necrosis factor alpha (TNF-α), which play a role in the tumor microenvironment." (PMID 41374067, 2025). "Our findings suggest that targeting proteins involved in RIPK1 pro-survival checkpoints and promoting direct RIPK1 activation is a viable mechanism to potentiate TNF-induced cell death and enhance the impact of immune cell-mediated tumor clearance." (PMID 41315176, 2025). "These cells also secrete IFN-γ and TNF-α, which inhibit tumor angiogenesis and induce M1 macrophage polarization." (PMID 40904467, 2025). "Pathway analyses indicate that prostate cancer–associated fibroblasts (PCa-CAFs) are more active in pro-inflammatory and tumor-related signaling (e.g., TGF-β, NF-κB, TNF), suggesting enhanced tumor-promoting capacity." (PMID 41514658, 2025). "M1-type macrophages are generated in response to granulocyte macrophage colony stimulating factors (GM-CSF or CSF2) and stimulated by IFN-γ, lipopolysaccharide, TNF-α, which share the same properties of anti-tumor and pro-inflammation." (PMID 41333471, 2025). "The data showed that CD8+ T cells in the combination therapy group had a markedly enhanced capacity to secrete key cytokines, including IFN‐γ and TNF‐α, both of which are essential for effective anti‐tumor immunity." (PMID 40552757, 2025). "CAR-Ms support CAR-T and CAR-NK cells by secreting cytokines such as IL-12 and TNF-α, which promote T cell expansion and NK cell activation, thereby increasing overall immune activity within the tumour site." (PMID 40624498, 2025). "A study in which TNF-α activity enhancement treatment was implemented found that TNF-α accelerates the death of tumor cells." (PMID 40351429, 2025). "Chronic exposure to TNF-α in the tumor microenvironment can activate survival pathways in tumor cells, resulting in chemoresistance." (PMID 40404908, 2025). "In triple-negative breast cancer (TNBC), TNFα exposure upregulates A20 expression, which promotes tumor growth and invasion, as evidenced in mouse xenograft models." (PMID 40214497, 2025).
tumor (continued). "IFN-γ has the antitumor properties of immune modulator, and TNF-α can also inhibit tumor cells by virtue of the immune function of the body." (PMID 40556745, 2025). "Tumour microenvironment‐driven cytokines, such as IL‐6 and TNF‐α, orchestrate systemic catabolic processes that link muscle wasting to nutritional dysregulation." (PMID 40631494, 2025). "TAN1 possesses anti-tumor properties; it releases cytokines such as IL-12 and tumor necrosis factor-alpha (TNF-α), which aid in the recruitment and activation of CD8+ T cells." (PMID 40909277, 2025). "High MMP1 expression was associated with increased activity in epithelial–mesenchymal transition signaling and TNFα/NF-κB pathways, which are known to promote tumor progression." (PMID 40394037, 2025). "In light of the ongoing need for non-invasive and accessible diagnostic tools in endocrine oncology, our findings suggest that TNF-α and Fascin merit further investigation as potential biomarkers of tumor activity." (PMID 40507492, 2025). "Tissue macrophages are categorised into tumour suppressive type 1 macrophages (M1-like), which produce IL-12 and TNFα, and tumour promoting type 2 macrophages (M2-like), which produce anti-inflammatory cytokines." (PMID 40430784, 2025). "The water extract of T. angustifolia inhibits the growth of Lewis lung cancer tumors in mice, increases serum levels of IL-2 and TNF-α, arrests tumor cells in the G1 phase, and induces tumor cell apoptosis." (PMID 40290444, 2025). "The 7D12-T-hIL-21 cells secreted more cytokines, including IFN-γ, TNF-α, and hIL-2, when cultured with tumor cells and exhibited better antitumor effector functions." (PMID 40722671, 2025). "Studies have shown that cytokines such as IL‐6 and TNF‐α play key roles in the tumor microenvironment in the context of elevated cytokines and bone metastasis progression." (PMID 40040540, 2025). "In our study, we observed that cytotoxic T/NK cells triggered TNF pathways, leading to the formation of HEVs, and possibly improved immune cell infiltration into the tumor." (PMID 40107247, 2025). "Tumour cells with upregulated stemness‐related ribosomal proteins (RPS7/RPL30/RPL8) evade TNF‐mediated clearance." (PMID 40770837, 2025). "In the early stages of CRC, TNF-α generates an inflammatory response in which immune cells such as neutrophils and macrophages are recruited to tumor site." (PMID 40558596, 2025). "Vδ2+ cells generally contribute to antitumor immunity by secreting IFN-γ and TNF-α and inducing tumor cell lysis through secreting perforin, granzyme B, and TRAIL." (PMID 40746558, 2025). "Elevated systemic CRP levels activate pro-tumorigenic signaling cascades, including NF-κB and MAPK pathways, inducing tumor cells to secrete proinflammatory cytokines, such as IL-6 and TNF-α." (PMID 40563367, 2025). "The bacterium can stimulate the NF-κB pathway, inducing the secretion of pro-inflammatory cytokines such as IL-6, IL-8, and TNF-α, thereby fostering a chronic inflammatory microenvironment that facilitates tumor initiation and progression." (PMID 41356485, 2025). "PDT-mediated tumor cell death induces local inflammation, accompanied by cytokine secretion, particularly TNF-α and IFN-γ." (PMID 40746718, 2025). "During early phases of tumor development, N1 TANs expressed high levels of TNF-α, ICAM-1, and Fas, promoting tumor cell apoptosis and enhancing CD8+ T-cell recruitment." (PMID 41584838, 2025). "This enhances tumor cell apoptosis in the presence of TNF and, when combined with T-cell bispecific antibodies or IC blockade, increased bystander tumor killing." (PMID 41583469, 2025). "Effector cytokines IFN-γ and TNFα are central to the activation, differentiation, and tumor-killing activity of CTLs." (PMID 40574846, 2025). "NK cells also release IFN-γ and TNF-α, which inhibit tumor growth, recruit other immune cells, and make the tumor environment less suppressive." (PMID 41375063, 2025).
tumor (continued). "M2 expresses high levels of CD163, CD206, CCL18, and CCL22, releasing anti-inflammatory (TGF-β, IL-4, and IL-13) and inflammatory (IL-6, IL-12, and TNF-α) factors, as well as tumor-promoting arginase-1 and VEGF, modulated by TME signals." (PMID 40940877, 2025). "Tumor necrosis factor (TNF)-related apoptosis-inducing ligand (TRAIL) is a potential therapeutic for cancer patients due to its tumor specificity." (PMID 40429781, 2025). "The study demonstrated that the cytokines VEGF and TNFα found in the tumor microenvironment enhance the interaction between YAP/TAZ and the transcription factor STAT3." (PMID 39936032, 2025). "This leads to reduced secretion of IFN-γ and tumor necrosis factor-α (TNF-α), ultimately resulting in the loss of cytotoxic T cell tumor-killing capacity and consequently diminishing the efficacy of ICIs." (PMID 40385461, 2025). "The secretion of TNF-α by these T cells can further modulate T cell activity, thereby enhancing anti-tumor responses." (PMID 39814702, 2025). "The downregulation of hsa-miR-34a-3p and miR-30e-5p, a known tumor suppressor targeting TNF-α, aligns with the observed increase in TNF-α expression in higher-grade tumors." (PMID 40565357, 2025). "For example, while TNF-α can induce tumor cell death, it can also promote tumor progression by activating NF-κB signaling in tumor cells." (PMID 40375990, 2025). "M1 macrophages play a pivotal anti-tumor role by mediating phagocytosis and antibody-dependent cell cytotoxicity, while releasing pro-inflammatory cytokines such as tumor necrosis factor alpha (TNF-α), interleukin-1β (IL-1β), and interleukin-6 (IL-6)." (PMID 40559655, 2025). "We also demonstrated that these cellular features are, at least in part, due to the presence of tumor-supportive molecules such as TNF-α, Tenascin-C, MMP-2, and SDF-1α in the CM secretome of ASCs and OC cells." (PMID 40072102, 2025). "Cell viability (MTT assay), migration (scratch assay), oxidative stress (TAS/TOS kits), TNF-α expression (qRT-PCR), and tumor marker levels (CA19-9, CEA, CA72-4, and CYFRA 21-1; CLIA) were evaluated." (PMID 40699763, 2025). "N1 neutrophils inhibit proliferation and release high levels of TNF-α, whereas N2 neutrophils, which have a longer lifespan, support cancer growth by producing pro-tumor factors like ROS, neutrophil extracellular traps (NETs), IL-6, IL-8, and MMP-9." (PMID 40636453, 2025). "They enhance the immune surveillance by secreting cytokines like IL-12 and TNF-α, which recruit and activate T cells to eliminate tumor cells." (PMID 40908470, 2025). "TNF, in particular, plays a critical role in promoting tumor angiogenesis, proliferation, invasion, and metastasis." (PMID 40821768, 2025). "TNF-α is a key pro-inflammatory cytokine that can induce tumor cell apoptosis and inhibit tumor proliferation and metastasis." (PMID 41157169, 2025). "Physiologically, TNF-α contributes to tumor surveillance by inducing apoptosis of malignant cells and enhancing cytotoxic T-cell and natural killer cell activity through TNFR1-mediated signaling pathways." (PMID 41302997, 2025). "Supporting these observations, we found that several kinases involved in DNA damage response, ATM, ATR, and PKCA, showed upregulated kinase activity in sensitized tumor cells following both T cell and TNF treatment." (PMID 41315176, 2025). "In vivo efficacy was evaluated in AOM/DSS-induced CRC mice, monitoring tumor growth, inflammatory markers (TNF-α, IL-1β, IL-6, MPO), and gut microbiota composition." (PMID 40733148, 2025). "Another effect of MDSCs is the release of cytokines that promote inflammation and tumor progression, such as TNF-α, IL-10, and IL-1β, while they encourage invasion, migration, and metastasis via MMPs." (PMID 41369383, 2025). "Enhanced IFN-γ and TNF-α cytokine release from supercharged NK cells promotes tumor differentiation by increasing MHC-class I surface levels in stem-like ovarian tumors." (PMID 41375063, 2025).
tumor (continued). "CD8+ T cells mediate tumor killing via perforin, granzyme, and TNF-α secretion; however, their cytotoxic functions are markedly impaired under hypoxic/acidic conditions." (PMID 41019983, 2025). "Functional assessments demonstrated that while both the DAP12-containing CAR and its predecessors exhibited comparable tumor-killing, the DAP12 construct produced lower levels of IFNγ, TNFα, and IL-2, during tumor cell lysis." (PMID 40948803, 2025). "For instance, HFDS-induced obesity reduces the production of granzyme and cytokines (TNF-γ, TNF-α), which in turn causes the depletion of CD8+ tumor-infiltrating lymphocytes (TILs) and ultimately speeds up tumor growth in a mouse model of colorectal cancer." (PMID 40011436, 2025). "AVM and CCMs release and respond to cytokines, such as vascular endothelial growth factors (VEGFs), fibroblast growth factor, angiogenin, and tumor necrosis factor-alpha, that promote neoplasia." (PMID 41458749, 2025). "By bridging IL-13Rα2+ tumor cells and CD3ε on T cells, the BiTE induces T-cell activation (CD69/CD25 upregulation), GZMB release, and production of inflammatory cytokines (IFN-γ, TNF-α), culminating in tumor-specific lysis." (PMID 41209565, 2025). "IRF5 is already highly expressed in dendritic cells and is required for TNF release, which enhances tumor cell killing." (PMID 38969706, 2024). "After predicting the importance of the TNF pathway in inhibiting tumor growth using network pharmacology methods, we verified the expression of TNF pathway targets via immunohistochemistry and quantitative PCR." (PMID 39000182, 2024). "Tumor necrosis factor (TNF) is a core cytokine in mammals, initially identified for its capacity to induce necrosis in tumor cells." (PMID 39723076, 2024). "These factors are crucial for the generation and function of TNF, which is produced by macrophages with tumor-killing effects." (PMID 38817865, 2024). "Consistent with our previous report, we observed significantly increased mRNA levels of TNF-α and IL-6 in the tumor tissues of AOM/DSS-treated VDUP1 KO mice compared to those in the tissues of WT mice." (PMID 39272794, 2024). "IFNα/β can also activate the NF-κB pathway as well as TNFα expression, inducing cell survival and protecting tumor cells against apoptotic stimuli in a variety of cancer types." (PMID 38632238, 2024). "Co-treatment of IFN-γ and TNF-α induced rapid death of dMMR tumor cells by inducing PANoptosis including pyroptosis, apoptosis, and no necrosis." (PMID 38740747, 2024). "Studies have shown that tumor-infiltrating monocytes, macrophages, and neutrophils secrete large amounts of pro-inflammatory cytokines such as IL-6, IL-8, and TNF-α, promoting tumor development in CAC models." (PMID 38516408, 2024). "The presence of the HPV has been associated with increased inflammatory cytokines (IL-1, IL-6, IL-17, TGF-β, TNF-α, and NF-kB) and tumor progression." (PMID 38994984, 2024). "Whereas PGD2 stimulation significantly inhibited NF-κB and TNF-α signaling, resulting in an anti-tumor effect." (PMID 38704736, 2024). "NF-κB is overexpressed in the PCa TME and regulates the expression of numerous tumor-promoting genes including cyclin-D1, IL-6, TNFα, VEGF, IL-8 and IL-1β." (PMID 39335188, 2024). "Among these, the most significantly enriched pathway was TNF signaling, which is known to affect tumor migration and apoptosis." (PMID 39000182, 2024). "TNF-α plays a complex role in tumor immunity, often used as a tool to regulate immune cells and kill tumor cells." (PMID 38903721, 2024). "Overexpression of inflammatory factors promotes tumor development, while targeting inflammatory mediators, such as chemokines, cytokines (TNF-α and IL-1β), and key transcription factors (NF-κB and STAT3), reduces cancer growth and spread." (PMID 38502348, 2024). "And the CTL mainly through the degranulation or death receptor pathway expresses FasL and secretes TNF specifically to kill tumor cells." (PMID 38261253, 2024).